IL1B (interleukin 1 beta)
Diseases named in the same sentence as IL1B in open-access papers (continued):
Sharing a sentence is not in itself a finding about the gene and the disease.
tumor (continued). "Different works have shown that in vitro stimulation of tumor cell lines by soluble factors such as IL-1β, TNFα, IL-6 or TGFβ can enhance c-Met expression." (PMID 34771724, 2021). "It had been proposed that anti-IL-1β treatment decreased the inflammation that would prove significant in progression to tumor development." (PMID 34571989, 2021). "Only IL-1β, measured in tumour tissue, demonstrated insignificantly higher expression among male patients: 10.662 (IQR: 4.058–18.640) vs. 7.649 (IQR: 2.031–14.136)." (PMID 33658555, 2021). "In murine models, depletion of macrophages/microglia has led to a reduction in tumor growth and in line with this, some factors released by GAMs such as IL-6, IL-1β, EGF, STI-1 and TGF- β can promote tumor growth." (PMID 33802571, 2021). "As inflammation progresses, it promotes the production of tumor-promoting cytokines such as IL-11, IL-1β, and IL-6, which support the survival, growth, and metastasis of tumor cells." (PMID 34150765, 2021). "In the tumor microenvironment, macrophages produce IL-1β, which leads to the recruitment of myeloid cells from the bone marrow and their differentiation into immunosuppressive macrophages." (PMID 33801846, 2021). "While present at a low level, IL-1β can induce effective anti-tumor immunity and suppress tumor formation." (PMID 34577552, 2021). "IL1β is known to be highly expressed in the tumor microenvironment of various cancer types, and drives many malignant processes such as initiation, proliferation, and metastasis." (PMID 34901003, 2021). "Meanwhile, IFN-γ, TNF-α, IL-2, and IL-1β play crucial parts in killing tumor cells according to previous researches." (PMID 34721026, 2021). "In pancreatic cancer, ATP-induced NLRP3 inflammasome activation accelerates IL-1β production that subsequently increases tumour cell proliferation." (PMID 33918087, 2021). "In inflammatory immune cells such as macrophages and neutrophils, the activation of NF‐κB activates the expression of inflammatory cytokines such as TNFα, IL‐1β, and IL‐6, thereby promoting the proliferation of malignant cells and tumor stromal cells." (PMID 34977871, 2021). "This raises the possibility of using anti-IL1β to prevent such tumor-mediated and therapy-induced proinflammatory events that sensitize tumors to chemotherapy." (PMID 34066976, 2021). "Polarized M1-like macrophages in the TME, following Salmonella treatment, produce significant amounts of proinflammatory cytokine Interleukin-1β (IL-1β), and that increase in IL-1β corresponds to tumor regression." (PMID 34829795, 2021). "The activation of ERβ by LY500307 promotes the secretion of IL-1β and enhance the infiltration of neutrophils in cancer tissue, which inhibits the tumor progress and lung metastasis." (PMID 34098945, 2021). "Our results showed that LyeTx I-b and carboplatin treatments significantly suppressed proinflammatory IL-1β expression in the lung and primary tumor." (PMID 34572719, 2021). "Hyper-activation NLRP1 inflammasome led to decreasing of tumor cells’ death and increased inflammatory microenvironment driven by IL-18 and IL-1β secretion, which has been proposed as a common mechanism of NLRP1 serving an instigator." (PMID 33658393, 2021). "Cluster 5 (tumor core EC type III: Co3), were mainly derived from tumor core and were characterized by upregulation of immune-activated genes including IL1B, ACKR1, SELE, and VACM1, which are associated with inflammation and immune cell recruitment." (PMID 34228647, 2021). "L1CAM expression can induce IL-1β secretion and NF-κB activation not only in tumor cells but also in immune cells." (PMID 34659539, 2021). "Inflammatory markers levels are dependent on tumor types, but high level of CRP, IL-6, IL-1β have been associated with poor prognosis." (PMID 34867341, 2021). "Researchers have suggested that AIM2 is able to activate inflammasomes, and act as a tumor suppressor by inducing IL-18 and IL-1β in GC cells." (PMID 33859277, 2021).
tumor (continued). "Our data illustrate that anticancer cellular immunity can be safely promoted with an IL-1β-based AcTakine, which synergizes with other immunotherapies for efficient tumor destruction." (PMID 34772757, 2021). "IL-1β, another member of the interleukin family, promotes tumor development by driving chronic inflammation, tumor angiogenesis, and induction of immunosuppressive cells." (PMID 33816512, 2021). "Our data show that IL-1B drives the recruitment of innate immune cells, and whilst IL-1B is protective in the primary tumour, it drives metastasis in bone." (PMID 34290237, 2021). "IL-1B has tumor-promoting effects in many cancer types via promotion and enhancement of angiogenesis and metastasis." (PMID 34439305, 2021). "miR-146a regulates IL-1β expression, and IL-1β plays an important role in tumor progression by enhancing angiogenesis, amplifying myeloid-derived suppressive cells (MDSCs) and shifting macrophages towards an M2 phenotype." (PMID 34790566, 2021). "She demonstrated that metastatic tumor cells engage in reciprocal interactions with bone marrow adipocytes to evade therapy and provided evidence that targeting IL-1β or lipolysis improves tumor cell response to anti-cancer therapy with docetaxel." (PMID 34335478, 2021). "Recently, it has been proposed that CAFs sense DAMPs and thus activate the NLRP3 inflammasome pathway, leading to proinflammatory signaling and IL-1β release, which promote tumor progression and lung metastasis." (PMID 34064909, 2021). "In summary, ZC3H12D in NK cells selectively captures nex-IL1β-mRNA enriched in the tumor-stimulated lung microenvironment and transports it into the nucleus." (PMID 34135341, 2021). "In conclusion, we found that exosomes exhibit increased secretion of IL-1β, IL-6, and IL-8 in CAFs, promoting fibroblast activation, stimulation of Wnt signaling pathway, tumor cell proliferation and migration, and cancer growth." (PMID 34261453, 2021). "Tumor-bearing mice had significantly elevated hepatic expression of the pro-inflammatory cytokines IL-1α, IL-1β, TNF-α, Cxcl9, and Cxcl10 compared to tumor-free mice." (PMID 34445729, 2021). "Interleukin1β (IL-1β) is considered an essential regulatory factor that promotes tumor progression, metastasis and immunosuppression." (PMID 33859939, 2021). "CRP acts on the microglia through IL-1β, which protects endothelial cells from starvation-induced death and thereby contributes to tumor angiogenesis and progression." (PMID 33747971, 2021). "In EBV‐associated NPC, EBV and irradiation‐induced AIM2 inflammasome activation lead to mature IL‐1β release that promotes tumor proliferation." (PMID 34014039, 2021). "IL-1β is a classic pro-inflammatory cytokine secreted by TAMs, which has been found to induce immunosuppression in many tumor types." (PMID 34386431, 2021). "We also observed that IL-1B promotes macrophage recruitment to the primary tumour site, potentially controlling macrophage polarisation and localisation." (PMID 34290237, 2021). "In support of our findings that IL-1B drives the infiltration of innate immune cells with putative tumour-killing capacity, by inhibiting M2-like macrophages, we found a reduction in CD34+ blood vessels in tumours overexpressing IL-1B." (PMID 34290237, 2021). "In mice, a novel Ly6C-negative MDSC subset has been reported to target NK cells after activation by tumor-released IL-1β, whereas in melanoma patients, M-MDSC are activated by PGE2 and impair NK cell-mediated cytotoxicity through the release of TGF-β." (PMID 33917501, 2021). "Another molecule is adenosine triphosphate (ATP), which can attract monocytes and DCs to tumours by a purinergic receptor P2 × 7-dependent pathway and promote the secretion of pro-inflammatory cytokines such as IL-1β and IL-18." (PMID 34281259, 2021). "IL-1β is traditionally regarded as a proinflammatory and procarcinogenic cytokine; however, both tumor-promoting and tumor-inhibiting effects are described." (PMID 35111698, 2021).
tumor (continued). "We also found increased expression of Il-1β, Il-6, and Ifn- γ in tumor stroma from Trpa1-/- group compared to wild type animals." (PMID 34041030, 2021). "IL1B along with TGFβ are the most prominent soluble factors inducing NCFs to CAFs and help tumor cells in escaping from chemotherapy." (PMID 34083590, 2021). "Tumor cell-derived IL-1β contributes to neutrophil infiltration since depletion of tumor cell-derived IL-1β significantly decreases the stromal accumulation of CD11b+ Gr1+ MDSC and CD11b+ Ly6G+ TANs." (PMID 34439836, 2021). "We found that tumor progression is characterized by constitutive inflammasome activation, increased IL-1β secretion, and reduced endogenous NPs expression." (PMID 34070682, 2021). "Tumor infiltration and activation of antigen-presenting cells and immune effector cells is mediated by several cytokines such as TNFα, IL-1β, IL-6 secreted in the tumor." (PMID 34830880, 2021). "TGFβ and IL-1β can be released by CAFs and can regulate the proliferation, metastasis and invasion of tumor cells." (PMID 34895039, 2021). "Further, IL-1β regulates hypoxia in the tumor mass by suppressing miR-101 expression through the COX2-HIF1α pathway." (PMID 34684819, 2021). "Most studies suggest that IL-1β plays an important role in promoting tumor cell proliferation, invasion, and metastasis." (PMID 34805183, 2021). "Contrary to the serum profile, urine from OH-BBN induced C57BL/6 mice displayed increased levels of the pro-inflammatory cytokines Ccl3 and Il1β, as well as an upregulation of tumor promoting Ppp1r2, Pak4, tumor growth marker Nadk, and Dctn2." (PMID 34232958, 2021). "While the classical IL-6 signaling pathway decreases the pro-inflammatory cytokines TNF-α and IL-1β, the trans-signaling pathway activates these pro-inflammatory pathways leading to chronical inflammation and tumor promotion." (PMID 34574641, 2021). "The changes of the gut microbiota composition and gene functions caused by HCC including the increase of tumor‐promoting chemokines, such as LPS‐induced CXC chemokines, and the decrease of tumor‐inhibiting chemokines including IFN‐γ, IL‐1β, and IL‐12." (PMID 34026439, 2021). "Anthracyclines induce pro-inflammatory responses by increasing tumor necrosis factor α (TNF-α), IL-1β, and IL-6, leading to tumor cell death." (PMID 35127869, 2021). "IL-1β, in turn, contributed to tumor progression through upregulation of VEGF-A, hereby promoting angiogenesis." (PMID 34944905, 2021). "Both tumour and microenvironment-derived IL-1B induce the recruitment of immune cells with a pro-inflammatory, anti-tumour profile." (PMID 34290237, 2021). "We found an increase in F4/80+ macrophages in tumours growing in IL-1B−/− mice in the periphery of the tumour compared to the core of the tumour." (PMID 34290237, 2021). "In primary tumours, IL-1B inhibited growth, by impairing the infiltration of innate immune cell subsets with potential anti-cancer functions but promoted enhanced tumour cell migration." (PMID 34290237, 2021). "Here, we found that the pro-inflammatory factors—IL-1β, IL-6, and IL-8—were significantly increased in fibroblasts treated with exosomes derived from tumor cells." (PMID 34261453, 2021). "The results were consistent with those in tumor cells, where ERp29 upregulated miR-135a-5p expression and downregulated levels of IL-1β and active form of caspase-1, suggesting that this mechanism is generalized but not cancer specific." (PMID 34667160, 2021). "Macrophage-derived TNF-α and IL-1β are strong inducers of IL-6 in tumor cells, a cytokine that in turn promotes intraosseous tumor growth, osteoclastogenesis, and osteolysis." (PMID 34064859, 2021). "Tissue damage occurring during tumor development and the release of alarm cytokines such as IL-1α, IL-1β, and TNFα induce the production of IL-6, IL-10, IL-11, and IL-23 by tissues and myeloid cells." (PMID 33498483, 2021).
tumor (continued). "In the AOM/DSS CRC mouse model, colon tissue from tumor-bearing mice showed significantly higher IL-1β production than that from naïve mice." (PMID 33578830, 2021). "MSCs are originally silent but become aggressive after receiving activation signals from tumor-derived pro-inflammatory cytokines, such as TNFα and IL1β, and/or ligation of the TLRs, such as TLR2, TLR3, and TLR4, that are expressed on MSCs." (PMID 33535613, 2021). "IL-1β released by M1 macrophages induces the expression of co-inhibitory molecules in tumor cells, which hampers the direct anti-tumor effect of cytotoxic T cells." (PMID 34248982, 2021). "The host-tumour interface and the resulting sequestration of the pro-inflammatory cytokine Il-1β is critical in cachexia development." (PMID 33907915, 2021). "Before examining potential tumor suppressors, we found that the levels of IL1β, Runx2, MMP9, TGFβ, and Snail in EO771 cells were downregulated by osteocyte-derived CM, and their levels were further reduced by the overexpression of the three selected genes." (PMID 33802279, 2021). "For example, overproduction of IL-1β resulting from constitutive NLRP3 inflammasome activation caused auto-inflammation and enhanced tumour progression in melanoma." (PMID 33918087, 2021). "A large number of studies indicate that TNFα and IL-1β promote disease progression by acting directly on the tumor cells and by affecting different components of the TME, including immune cells." (PMID 33806906, 2021). "M1 generates reactive oxygen species (ROS) and pro-inflammatory cytokines, such as IL-2, IFN-γ, TNF-α, and IL-1β, which play essential roles in killing tumor cells." (PMID 34721026, 2021). "These cells hold significant influence over tumor ECs through the wide range of secretory factors including IL-1β, VEGF, FGF2, TGFα, hepatocyte growth factor (HGF), and angiopoietin 1 (ANG1)." (PMID 34987525, 2021). "A notable example is the inactivation of liver kinase B1 (LKB1), a tumor suppressor, which reportedly promotes neutrophil recruitment and pro-inflammatory cytokine (IL-1β, IL-6, IL-33, and CXCL7) production to suppress T cell infiltration and function." (PMID 34063828, 2021). "Several studies including ours reported that CAFs-secreted cytokines including IL-6, IL-8, TGF-β, and IL-1β participated in tumor progression through holding communication between CAFs and cancer cells." (PMID 34930899, 2021). "Accordingly, when TNBC cells were continuously stimulated by TNFα + IL-1β, their ability to secrete factors that induce the recruitment of monocytes and neutrophils to matrigel plugs in vivo was reduced by treating the tumor cells with a glycolysis inhibitor." (PMID 34072893, 2021). "Downstream effectors of inflammasome signaling, IL-1β, and IL-18, have also been demonstrated to promote tumor angiogenesis 4, metastasis 5, and immune evasion 6 through paracrine and autocrine mechanisms." (PMID 34815793, 2021). "Targeting the ERK5 pathway with XMD8-92 resulted in a decrease in asbestos-induced IL-1β secretion, colony formation, and tumor growth in malignant mesothelioma." (PMID 33572742, 2021). "We used NCFs, their conditioned media (CM), and cocultures with tumor cells to characterize the IL1β-mediated crosstalk between both cell types." (PMID 34066976, 2021). "For example, MyD88 and IL-1β have protumor activities at an early stage and antitumor activities at a later stage in mouse tumor models." (PMID 33946044, 2021). "IL-1α, IL-1β, and IL-1R which are commonly expressed by tumor-infiltrating immune effector cells and tumor stromal cells are responsible for shaping the tumor microenvironment." (PMID 34220337, 2021). "More importantly, it has been shown to significantly inhibit tumour growth and recurrence as compared to pro-IL-1β, indicating the importance of inflammasome activation in promoting the production of IL-1β for tumour suppression." (PMID 33918087, 2021).
tumor (continued). "IL-1β and IL-17 expression was also higher in the tumour samples of taken from patients with a shorter smoking history, but only insignificantly." (PMID 33658555, 2021). "In breast cancer and Lewis lung carcinoma metastatic model, IL-1β induces IL-17 production by tumor-infiltrating γδT cells." (PMID 34298791, 2021). "L-Kyn mediated AhR activation promotes tumor growth with elevated levels of inflammatory cytokines (IL-6, IL-8, and IL-1β) and a decreased frequency of infiltrating cytotoxic CD8+ T cells in TME." (PMID 34867973, 2021). "Smac mimetics lead to tumor cell apoptosis when combined with agents that induce IL-1β, IFN-β, TNF-α and TRAIL." (PMID 34172082, 2021). "Note that AIM2 can activate inflammasomes in GC patients and act as a tumor suppressor by inducing IL-18 and IL-1β, indicating that AIM2 is an important prognostic indicator in GC patients, which is consistent with our study." (PMID 34680930, 2021). "In conclusion, these data suggest that tumour derived IL-1B activates the innate immune response with potential anti-tumour functions." (PMID 34290237, 2021). "AIM2 can activate inflammasomes in GC patients and act as a tumor suppressor by inducing IL-18 and IL-1β." (PMID 34680930, 2021). "Upon ATP binding to the P2RX7 receptor on dendritic cells, IL-1β is released, which draws tumor specific T lymphocytes into the TME." (PMID 34869014, 2021). "The present study confirmed the profound increase in pro-inflammatory markers (Il6, Il1β, and Ptgs2) in tumor compared to peri-tumoral tissue in mice of all genotypes." (PMID 34526660, 2021). "IL-1β abundance in the tumor environment and its overexpression have already been associated with the progression of different cancer types, including prostate cancer (PCa)." (PMID 34064909, 2021). "Macrophages can contribute to tumor-promoting inflammation, e.g., by secretion of proinflammatory cytokines, like IL-6, IL-1β, TNFα." (PMID 33919517, 2021). "Innate immune cells of the myeloid lineage are the principal sources of the inflammatory cytokines tumor necrosis factor (TNF), interleukin 1 beta (IL-1β), and interleukin 6 (IL-6) in the tumor microenvironment (TME)." (PMID 33808059, 2021). "High content of IL-1β correlates with tumor migration, invasiveness, and higher aggressive tumor phenotype." (PMID 33663382, 2021). "One of the Th2 inflammatory pathways favoring tumor protection in BC relies on the secretion of IL-1β from primary BC induced by T cell cytokines and thymic stromal lymphopoietin (TSLP)." (PMID 34602858, 2021). "NOX5 activated intratumoral Src/nuclear factor‐κB signaling to stimulate secretion of tumor necrosis factor‐α (TNF‐α), interleukin‐1β (IL‐1β), and lactate from tumor cells." (PMID 34459125, 2021). "In response to TLR4 signaling in macrophages, the E2 mediated the secretion of inflammatory cytokine (IL-1β, IL-6, and TNF-α) and contributed to the tumor-associated inflammation and cancer immune escape." (PMID 34098945, 2021). "MRP8-restricted expression of a functional Ncf1 restored the release of IL-1β from neutrophils and the susceptivity to tumor colonization." (PMID 34257370, 2021). "Tumor cells undergoing pyroptosis release IL‐1β, IL‐18, and various DAMPs, which are signals used to activate and recruit DCs or macrophages to phagocytose the pyroptotic cells and promote their maturation." (PMID 34459122, 2021). "All tumor-irradiated Sirpα−/− mice developed inflammatory responses with an elevated serum level of cytokines TNFα, IL-1β, IL-12, and IFNγ, whereas WT mice treated with the same RT regimen did not exhibit similar increases in cytokines." (PMID 34050181, 2021). "Garcinia livingstonei T. Anderson (GLT) elevates the expression level of iNOS and IL-12, and reduces the expression levels of IL-6, TNF-α, Arg-1, and IL-1β on TAMs to impede the tumor progression through the inhibition of STAT3, JNK, and ERK signaling pathway." (PMID 33748122, 2021).